IDH1 (isocitrate dehydrogenase (NADP(+)) 1)
Diseases named in the same sentence as IDH1 in open-access papers (continued):
Sharing a sentence is not in itself a finding about the gene and the disease.
glioma (continued). "Results from this prospective, open-label, phase Ib study show that the combination of metformin and chloroquine has a favorable toxicity profile but no clinical activity in patients with IDH1-mutated chondrosarcoma, glioma and intrahepatic cholangiocarcinoma." (PMID 34069550, 2021). "Likewise, ATRX-mutant patient-derived glioma cells were found to be more resistant than a wild-type control to senescence induced by Temodar, Imatanib, Doxorubicin, or CDKi treatment, in an IDH1-mutant background." (PMID 34763709, 2021). "Interestingly, WHO grading also showed significance for IDH1-R132H-nm gliomas, which is in line with a previous publication." (PMID 33538917, 2021). "However, in IDH1 mutant patients, despite the rising histologic tumour grade of cancer, the onset age of glioma was constant." (PMID 34205437, 2021). "Despite the immune suppression role of IDH1 mutation, it is still unknown why patients with IDH-mutant glioma have prolonged overall survival and better clinical outcome." (PMID 34150663, 2021). "Because histone deacetylase (HDAC) enzymes are localized to methylated chromatin via methyl-binding domain proteins, IDH1/2mut gliomas may be more dependent on HDAC activity, and therefore may be more sensitive to HDAC inhibitors." (PMID 34424450, 2021). "Moreover, STOX1 expression was also found to be significantly higher in all IDH1-mutant gliomas in TCGA and GBMs in CGGA compared with their IDH1 wild-type counterparts." (PMID 34722888, 2021). "Molecular diagnosis prior to invasive testing may guide management and predict outcomes for patients, as has been seen to be the case with IDH1 positive gliomas." (PMID 34638495, 2021). "The survival association in proneural glioblastoma was independent of the absence or presence of mutations in the genes encoding isocitrate dehydrogenase (IDH)-1 or IDH-2, a molecular marker that defines a clinically and molecularly distinct glioma entity with proneural gene expression." (PMID 33575479, 2021). "Finally, increased expression of TRIM22 correlated with other features of more aggressive gliomas, including wild-type IDH1 (P < 0.001) and wild-type ATRX (P = 0.0054)." (PMID 32814880, 2021). "IDH1 was a key rate-limiting enzyme in the Krebs cycle, and IDH1 mutation was a favorable independent prognostic factor for PFS in glioma, and it also played an important role in the time of tumor recurrence and outcome of gliomas." (PMID 34778058, 2021). "The pairwise similarity heatmap reveals two major clusters referring to gliomas with and without mutations of the IDH1/2 gene." (PMID 34206856, 2021). "In contrast to gliomas, there is little evidence of IDH1 mutations in breast cancer, with only one reported case noted." (PMID 33367952, 2021). "Treatment planning and prognosis in glioma treatment are based on the classification into low- and high-grade oligodendroglioma or astrocytoma, which is mainly based on molecular characteristics (IDH1/2- and 1p/19q codeletion status)." (PMID 34073309, 2021). "Importantly, both IDH1 mutation and SVZ-negative tumors enabled favorable patient outcomes and longer time to relapse, whereas IDH1-wild glioma with SVZ-positive displayed a significantly worse prognosis and shorter time to relapse." (PMID 34490090, 2021). "In the present study, we aimed to assess the clinical outcomes achieved by patients with grade II–III gliomas harbouring non-canonical IDH1 mutations." (PMID 33669525, 2021). "Furthermore, TBR/ADC combination had a higher diagnostic accuracy than each single imaging method for high-grade and IDH1-, hTERT-, and EGFR-mutated gliomas." (PMID 34912706, 2021). "Having found a high frequency of IDH1 and IDH2 mutations in subtypes of gliomas, we hypothesised role in long-term follow-up studies, finding that both IDH1 and IDH2 mutations are strong prognostic factors, supporting other data." (PMID 35996504, 2021).
glioma (continued). "In this study, we screened the Cancer Genome Atlas (TCGA), Chinese Glioma Genome Atlas (CGGA) and GSE16011 datasets and found that TRIP13 mRNA expression elevated in advanced grade of gliomas and isocitrate dehydrogenase 1 wild type (IDH1-WT) in lower-grade glioma." (PMID 34066132, 2021). "The training and testing experiments on 217 pathologically verified IDH1 genotyped glioma cases from multi-resource validated that our fully automated machine-learning model predicted IDH1 genotypes with greater accuracy and reliability than models that were based on radiological imaging data only." (PMID 36303770, 2021). "By contrast, IDH1 wild-type gliomas exhibited an activated glycolysis pathway." (PMID 33627136, 2021). "Interestingly, D-2HG also affects BCAT1, possibly due to direct inhibition of enzyme activity or DNA hypermethylation within the main promoter region of BCAT1 in IDH1-mutant gliomas." (PMID 34067762, 2021). "In Non-Redundant, the frequency of IDH1 mutation was 100% in lower-grade glioma, and cancer types with IDH2 mutation >10% included acute myeloid leukemia, myelodysplastic syndromes, and primary central nervous system lymphoma." (PMID 34440884, 2021). "A previous study performed a meta-analysis of IDH1 and IDH2 mutations from 55 different studies with 9,487 glioma tumors found both mutations were independently and statistically significantly associated with better OS and PFS of glioma patients." (PMID 35996504, 2021). "Alternatively, tumor-associated glymphatic pathway remodeling may be responsible for the differences in glymphatic function between IDH1 wild-type and IDH1 mutant gliomas." (PMID 34631582, 2021). "Thus, this review is focused on the opposed interplay between IDH1 mutations and the canonical WNT/β-catenin in gliomas development in young adults." (PMID 34070746, 2021). "The studied population was composed of 433 patients with WHO grade II–III IDH1 mutant gliomas." (PMID 33669525, 2021). "Moreover, IDH1 wild-type gliomas displayed a significantly increased expression of glycolytic enzyme genes (LDHA, HK2, PGAM2, PGK1, PKM, TIGAR) compared to IDH1-mutant gliomas as shown in heatmaps." (PMID 33493139, 2021). "Subsequently, it was uncovered that the expression of IDH1mt could mirror the G-CIMP in low-grade glioma, and IDH1/2mt was found to increase the global level of 5-mC." (PMID 33842477, 2021). "In the genetically engineered U87IDHmut model as well as in two patient-derived BT257 and SF10417 mutant IDH1 glioma models, treatments with either AG-881 or BAY-1436032 resulted in a consistent reduction in 2-HG, confirming brain penetration and action of the IDH inhibitors." (PMID 33668509, 2021). "In addition to PE and PCho, levels of phosphatidylinositol (PI) lipids are reported as being increased when comparing mutIDH1R132H and WT IDH1 glioma PDXs in mice." (PMID 35028610, 2021). "IDH1 mutations have not been reported in pediatric gliomas, suggesting that IDH1 mutations are only restricted to astrocytomas and oligodendrogliomas in young adults." (PMID 34070746, 2021). "Studies regarding the influence of scalp block on high-grade gliomas have been inconclusive, possibly because the condition’s most important genetic mutation profile, namely the isocitrate dehydrogenase 1 (IDH1) mutation, had not been analyzed." (PMID 34389754, 2021). "It was suggested that lactate is actively imported and converted into α-KG in IDH1 mutant gliomas, and that supplement of metabolic substrates is dependent on lactate, which can alleviate cells from the metabolic stress that results from defective isocitrate processing." (PMID 34516556, 2021). "Small molecule inhibitors of the mutant IDH1 protein have been developed to target glioma cells." (PMID 32542524, 2021). "Therefore, prior to investigating patient-derived (BT257 and SF10417) mutant IDH1 glioma models, we first performed a small-scale study investigating the effect of AG-881 treatment on mice with orthotopic U87IDHmut tumors." (PMID 33668509, 2021).
glioma (continued). "WHO grade, age, diagnosis, isocitrate-dehydrogenase 1 (IDH-1) wild type (wt) of glioma patients." (PMID 34079819, 2021). "IDH1 gene mutations in gliomas exhibit two unique features: lack of loss of heterozygosity and lack of apparent inactivating mutations such as truncations or frame shifts." (PMID 34707087, 2021). "We conclude that IDH1-mutant glioma is characterized by significant genetic changes that could contribute to a better prognosis in glioma patients." (PMID 34503108, 2021). "The patients with HOXB7 high expression, IDH1 wild-type and 1p/19q non-codeletion subgroups all had similar survival trends, which further illustrate the association between HOXB7 and IDH1 wild-type gliomas, as well as 1p/19q non-codeletion gliomas." (PMID 34458259, 2021). "Moreover, there was a higher infiltration of NK cells in IDH1 mutant glioma patients, and this was correlated with a better prognosis." (PMID 34925438, 2021). "Generally, glioblastoma, the most aggressive form of glioma, does not harbor an IDH1 mutation and requires establishment of new treatments and biological targets." (PMID 34503108, 2021). "Therefore, immunohistochemical staining (IHC) for isocitrate dehydrogenase 1-R132H (IDH1-R132H) mutation and PSMA expression was performed on the paraffin embedded tissue samples of 122 treatment-naive glioma patients." (PMID 34209106, 2021). "Secondary GBMs with IDH1 mutations are mostly developed from grade II gliomas, whereas secondary GBMs lacking IDH1 mutations are progressed from grade III gliomas via additional genetic, epigenetic, or chromosomal alterations making them more aggressive." (PMID 34356864, 2021). "The frontal lobe predominance of IDH1-mutant gliomas may be because this type of tumors probably originates from glial progenitors in the forebrain subventricular zone." (PMID 33553421, 2021). "To date, cancer-associated IDH1/2 mutations are commonly found in acute myeloid leukemia (~20%), melanoma, cartilaginous tumors (56–70%), cholangiocarcinoma (8.5–20%), and WHO II/III gliomas (~80%)." (PMID 34571995, 2021). "IDH1 wild-type gliomas are known to behave more aggressively than IDH1 mutant gliomas." (PMID 34631582, 2021). "Immunohistochemistry for the mutant specific IDH1-R132H is routine for diffuse adult glioma." (PMID 34020723, 2021). "It is interesting to clarify whether IDH1 mutation and tumor-SVZ distance >10 mm would serve as specific biomarkers that are predictive of effective response to current therapy for gliomas." (PMID 34490090, 2021). "IDH1/2 mutation changing DNA methylation and/or histone methylation may lead to CTCF binding dysfunction in gliomas causing aberrant PDGFRA activation." (PMID 34341417, 2021). "IDH1-R132H decreases the activity of the PI3K/Akt pathway in glioma cells." (PMID 34070746, 2021). "Hotspot mutations in IDH1, of which IDH1R132H is the most prevalent in glioma and chondrosarcoma, lead to heterodimeric enzymes (IDH1WT/MUT), loss of wild-type IDH1 enzyme function and a neomorphic IDH1 activity that converts αKG into the oncometabolite D-2-hydroxyglutarate (D-2HG)." (PMID 34069550, 2021). "Unlike gliomas where IDH1 R132H mutation is predominant and can be diagnosed by immunohistochemistry, the distribution of IDH1 mutations is more heterogeneous in chondrosarcoma with R132C being the most frequent followed by R132G and R132L." (PMID 34085407, 2021). "Combining IDH1 inhibitor with anti-PD-1 improved prognosis in C57BL/6J mice bearing IDH1mt glioma." (PMID 33842477, 2021). "Additionally, there is 2- to 4-fold longer median survival in patients with IDH1 mutant glioma compared to those with IDH1 wild-type glioma." (PMID 35174170, 2021). "IDH-mut with or without 1p19q co-deletion glioma patients had lower GSDMD expression that those with IDH1-wt, which indicated strong association between GSDMD and molecular features and therefore with its malignancy." (PMID 34830775, 2021).
glioma (continued). "Thus, the integration of multi-parametric imaging features for automated analysis of cross-modal biomedical data improved the prediction accuracy of glioma IDH1 genotypes." (PMID 36303770, 2021). "The final drug on the list, Elesclomol, was predicted to be more effective in IDH1 mutant tumors, especially gliomas, an association not previously reported in the literature." (PMID 34548481, 2021). "In conclusion, IDH1 wild-type gliomas and gliomas with larger peritumoral brain edema volumes were associated with a lower ALPS index, which may reflect an impaired glymphatic function." (PMID 34631582, 2021). "Prognosis of gliomas with IDH1/2 mutations is generally good, however, some gliomas exhibiting IDH1/2 mutations have similar prognosis as glioblastomas without IDH1/2 mutations." (PMID 34081618, 2021). "IDH1/2 mutations reduced the release of CXCL10 that attract the accumulation of CTLs, and increased the production of PD-L1, hinting the involvement of glioma cell metabolism in the dysfunction of CTLs." (PMID 34211978, 2021). "The results showed that BCAT1 is highly expressed in GBM versus lower grade gliomas and could represent the poor survival of IDH1 wild-type gliomas." (PMID 33493139, 2021). "In glioma, non-canonical (i.e. not IDH1 R132H or IDH2 R170C) IDH1 variants have different clinical characteristics and tend to arise in different locations in the brain compared with the canonical variants." (PMID 34854890, 2021). "We therefore sought to determine whether IDH1/2mut gliomas might be preferentially sensitive to HDAC inhibitors (HDACi), which are already being used to treat malignancies elsewhere in the body." (PMID 34424450, 2021). "BCAT1 is enriched in IDH1 wild-type gliomas and may relate to apoptosis, hypoxia and angiogenesis processes in tumor progression." (PMID 33493139, 2021). "Additionally, Duke University also has an ongoing clinical trial (NCT02193347) investigating the use of an IDH1 peptide vaccine in the treatment of recurrent grade II gliomas." (PMID 34572775, 2021). "Furthermore, we correlated PD-L1 expression with molecular glioma hallmarks such as MGMT-promoter methylation, IDH1/2 mutations, TERT promoter mutations and LOH1p/19q." (PMID 33963441, 2021). "Our data shows that IDH1/2mt gliomas are distinct when compared to other IDH1/2mt tumours in that they have a disproportionally high percentage of IDH1R132H mutations and raise the attractive clinical association between different rarer (codon 132) mutations and outcome." (PMID 33740099, 2021). "Many studies indicated that IDH1-mutant gliomas and codel gliomas have a better prognosis." (PMID 34422904, 2021). "Sequencing analyses revealed that KNS1451 did not harbor glioma-related driver mutations, such as IDH1/2, BRAF, and H3F3A, except for the TERT promoter C250T mutation detected by Sanger sequencing." (PMID 33387197, 2021). "Studies also have shown that FTO may play an oncogenic role via maintaining the stability of transcripts of avian myelocytomatosis viral oncogene homolog (c-Myc) and CCAAT enhancer binding protein alpha (CEBPA) in glioma, especially IDH1/2 mutant glioma." (PMID 33718165, 2021). "Interestingly, IDH1-mutant glioma cells were later shown to activate autophagy of the ER (ER-phagy) to survive the 2-HG-mediated ER stress." (PMID 34356864, 2021). "Therefore, although both IDH1 and IDH2 mutations are rare events in human cancer, the prevalence of IDH1 mutation in lower-grade glioma suggests a tissue-specific role in tumorigenesis." (PMID 34440884, 2021).
glioma (continued). "In addition, previous study has shown that the radiomic model can accurately predict the IDH1 mutation status of WHO grade II and III glioma by analyzing DTI images." (PMID 33163535, 2020). "Chen (2017) showed that the relationship between IDH1 mutations and seizures did not depend on the grade of the glioma." (PMID 32856857, 2020). "IDH1 mutations are driver mutations of low-grade gliomas and found in 80% but are not detectable in primary glioblastoma (GBM)." (PMID 31960234, 2020). "Further, IDH1 wild-type and chromosome 1p/19q non-co-deletion gliomas had significantly higher KDELC2 mRNA expression than mutated IDH1 and chromosome 1p/19q tumors." (PMID 32927743, 2020). "More importantly, we elucidated optimal combinations for IDH1 mutant glioblastoma and lower grade glioma GSCs with low dependencies on E&F, which could be an aid in clinical decision-making for these DIGs." (PMID 32120790, 2020). "We found recurrent glioma patients with R132H-mutated DNA of the gene isocytrate dehydrogenase 1 (IDH1) and patients without chromosome 1p/19q co-deletion were most likely sensitive to Notch inhibitors." (PMID 33004830, 2020). "However, several amino acid PET studies showed paradoxically higher tracer uptakes in IDH-mutant gliomas, especially with oligodendroglial components, compared with counterpart IDH1-wildtype tumours." (PMID 32382870, 2020). "Because we did not perform genomic sequencing of gliomas from all of these patients to identify the mutations in these gliomas, we did not know which patient(s) have IDH1/2 mutations." (PMID 32576825, 2020). "In fact, IDH1 and IDH2 mutations correlate with a better overall survival of glioma patients." (PMID 32316617, 2020). "Association of IDH1 and IDH2 gene mutations with clinical variables in glioma patients." (PMID 33552543, 2020). "A total of 66 gliomas were IDH1 wild type, while 34 were IDH1 mutant." (PMID 32051040, 2020). "The findings are compatible with IDH1 wild type glioma being more aggressive than IDH1 mutant type." (PMID 32582544, 2020). "Patients with IDH1-mut glioma have a better outcome than those with IDH1-wt glioma." (PMID 32993564, 2020). "The impact on survival by TMZ therapy irrespective of IDH1 mutation status was observed to be better in glioma cases." (PMID 33552543, 2020). "A perioperative study in patients with non-enhancing, IDH1-mutated, low-grade gliomas is being conducted to determine the concentration of ivosidenib and 2-HG in tumors following presurgical treatment with ivosidenib (clinicaltrials.gov NCT03343197)." (PMID 31028664, 2020). "Furthermore, glioma patients’ quality of life index, their tumor-related symptoms, IDH1 status, and tumoral miR-181b levels are important factors predicting patients’ survival time." (PMID 33050332, 2020). "IDH1/2 mutations should arise during embryonic development due to the somatic mosaic of mutant IDH1/2-expressing cells, such as IDH1 R132H/C/L/S or R100Q and IDH2 R140Q/G/W/L or R172K/G/M/Q/T/S, which are common mutations in gliomas (bold are the most frequent)." (PMID 31847543, 2020). "High level of RGS16 commonly gathered in glioma of mesenchymal subtype and wild‐type IDH1." (PMID 32319728, 2020). "Generating in vitro models by overexpression of the wild-type or mutated IDH1 can be a way to establish the glioma model containing IDH1-R132H, although this is not an accurate model for disease modeling." (PMID 33221817, 2020).